YBX1 (Y-box binding protein 1)
Diseases named in the same sentence as YBX1 in open-access papers (continued):
Sharing a sentence is not in itself a finding about the gene and the disease.
breast carcinoma (continued). "Knock down of YBX1 reduced breast cancer cell migration and invasion and could partially reverse the stimulative effects of AC073352.1 overexpressed on breast cancer metastasis." (PMID 34218256, 2021). "lncRNA AATBC could promote breast cancer migration and invasion through binding with YBX1 to activate the YAP1/Hippo signaling pathway." (PMID 34244473, 2021). "For example, a series of tRFs generated by Glu/Asp/Gly/Tyr tRNAs in the low metastatic breast cancer cell line MDA under hypoxia conditions competitively bind with oncogene YBX1 protein, which reduces the stability of oncogene transcripts and thus inhibits cancer metastasis." (PMID 34055648, 2021). "Moreover, there is a direct interplay between the oncoprotein Y-box binding protein-1 (YB-1) and IL-6, which affects breast cancer metastasis." (PMID 33123472, 2020). "By displacing YBX1 from these oncogenes, tRFs could arrest tumor progression in human breast cancer cell lines." (PMID 32890397, 2020). "YBX1 expression correlates with poor outcomes in breast cancer patients." (PMID 32587247, 2020). "Moreover, YBX1 interaction with mRNA has been shown to be involved in breast cancer progression, where microRNA miR-886 was shown to bind to YBX1 and downregulate NF-κB signaling." (PMID 33375283, 2020). "Several studies have revealed the functions of C1QBP in tumorigenesis are varied: for instance, C1QBP maintains oxidative phosphorylation for tumor cells, enhances cell chemotaxis and metastasis in breast cancer and suppresses the Y box binding protein 1 in renal cell carcinoma." (PMID 32025240, 2020). "In addition, siRNA against YBX1 in a normal ER- cell-line (MCF10A) resulted in significantly reduced cell-confluence and growth, even when compared to other breast cancer risk TFs46." (PMID 31428694, 2019). "Therefore, the enhanced expression of YBX1 is often reciprocally accompanied by the reduced expression of ER-dependent genes, which likely promotes breast cancer progression by driving ER-independent cell growth and survival." (PMID 30647855, 2018). "Our previous studies demonstrated that HER2 is positively correlated with YBX1 in breast cancer." (PMID 30647855, 2018). "However, the clinical significance of YBX1 in breast cancer should be discussed in the context of genes facilitating ER-dependent or ER-independent growth and survival." (PMID 30647855, 2018). "Development of therapeutic drugs by targeting YBX1 activation process could contribute to overcome breast cancer through inhibiting expression of predictive genes in present study." (PMID 30647855, 2018). "Our previous studies demonstrated a significant and reciprocal correlation between YBX1 and ER in breast cancers, and showed that the enhanced expression of YBX1 markedly downregulates the expression of ESR1 and induces acquired resistance to antiestrogen therapeutics." (PMID 30647855, 2018). "We further assessed whether genes positively or negatively correlated with YBX1 could predict the outcomes of breast cancer patients (n = 63) at Kyushu University Hospital." (PMID 30647855, 2018). "YBX1 promotes tumorigenesis and the malignant progression of breast cancer." (PMID 30647855, 2018). "YBX1 and CTPS1 as well as ESR1 and CTPS1 were found to be independently associated with the prognosis, supporting the idea that PRIN2 and PRIN5 play important roles in the prognosis of breast cancer patients." (PMID 30647855, 2018). "The increased or decreased expression levels of these genes correlated with the expression of YBX1 may thus limit the malignant progression of breast cancer." (PMID 30647855, 2018). "Hence, to obtain a better understanding of the functional role(s) of YB-1 in breast cancer metastasis, the YBX1 gene was knocked down in two highly aggressive TNBC cell lines, namely MDA-MB-231 and Hs578T cells." (PMID 28302118, 2017).
breast carcinoma (continued). "Upon induction in breast cancer cells, these tRFs suppress the stability of multiple oncogenic transcripts by sequence specific displacement of their 3′-UTRs from the RNA-binding protein YBX1." (PMID 27015120, 2016). "Notably, treatment of basal-like breast cancer cells with the MEK inhibitor PD98059 resulted in the inhibition of YBX1 function and the knock-down of YBX1 in breast cancer cells harboring activated RAS resulted in growth suppression." (PMID 21170361, 2010). "In breast cancer, YBX1 expression is discussed to be a potential marker of drug resistance and could possibly aid in selection of the appropriate adjuvant chemotherapy regime for breast cancers." (PMID 20428086, 2010). "Y-box binding protein-1 (YB-1) is an oncogenic transcription/translation factor that is overexpressed in a number of cancer types, including breast cancer, prostate cancer, bone cancer, lung cancer, colon cancer, muscle cancer and, most recently, pediatric brain tumours." (PMID 19036157, 2008). "Furthermore, tRFs mainly derived from tRNA-Glu, tRNA-Asp, tRNA-Gly, and tRNA-Tyr were demonstrated to competitively bind to Y-box-binding protein 1 (YBX1), which enabled the displacement of multiple oncogenic transcripts from the YBX1 protein in breast cancer cells." (PMID 35574338, 2022). "Moreover, AC073352.1 might be packaged into exosomes by binding to YBX1 in breast cancer cells resulting in angiogenesis." (PMID 34218256, 2021). "Y-box binding protein-1 (YB1), a DNA/RNA-binding protein containing a conserved cold shock domain (CSD), is commonly overexpressed and associated with poor clinical outcomes in a broad range of human carcinomas, including breast cancer, liver cancer and lung cancer." (PMID 32028981, 2020). "Our present study indicates that the expression of YBX1 and its correlated genes could be used to predict not only poor outcomes but also resistance to endocrine therapeutics and chemotherapeutics in patients with breast cancer." (PMID 30647855, 2018). "The expression of YBX1 together with the expression of its positively or negatively correlated genes may help to predict outcomes as well as resistance to endocrine therapies in breast cancer patients." (PMID 30647855, 2018). "Comparison of the expression patterns of the m5C machinery across breast cancer subtypes revealed that the m5C methyltransferase NSUN5 and the readers ALYREF, YBX1, and YBX2 were overexpressed in the basal subtype relative to normal tissue." (PMID 40918643, 2025). "Mechanistically, CD2BP2‐DT drives YBX1 phase separation to stabilize CDK1 and promote breast cancer progression." (PMID 39976088, 2025). "This flavonol was shown to inhibit the growth of breast cancer stem cells, MCF-7, which are resistant to doxorubicine, through the down-regulation of P-gp expression, Y-box binding protein 1 (YB-1) nuclear protein, and the CD44+/CD24− phenotype." (PMID 39859345, 2025). "CD2BP2‐DT mediates the phase separation of YBX1, thereby stabilizing CDK1 mRNA and promoting the proliferation of breast cancer cells." (PMID 39976088, 2025). "The results of the ActD rescue experiment showed that CDK1 mRNA stability was reduced in breast cancer cells following CD2BP2‐DT knockdown, and this reduction was partially reversed by YBX1 overexpression in the context of CD2BP2‐DT knockdown." (PMID 39976088, 2025). "Rescue experiments demonstrated that the inhibitory effect of stable CD2BP2‐DT knockdown on CDK1 expression was reversed by YBX1 overexpression in breast cancer, while the promoting effect of CD2BP2‐DT overexpression on CDK1 was inhibited by YBX1 knockdown." (PMID 39976088, 2025). "Conversely, CDK1 mRNA stability was increased in breast cancer cells after CD2BP2‐DT overexpression, but this increase was inhibited when YBX1 was knocked down during CD2BP2‐DT overexpression." (PMID 39976088, 2025).
breast carcinoma (continued). "In breast cancer, lncRNA AATBC functions as a Y-box binding protein 1 (YBX1) scaffold and controls Hippo signaling through lncRNA AATBC/YBX1/mammalian sterile 20 like kinase 1 (MST1) axis." (PMID 39313797, 2024). "KMT2D‐mediated H3K4me1 mark and YBX1 were colocalized at the TSS and promoter regions of the c‐Myc and SENP1 genes in breast cancer cells." (PMID 38967349, 2024). "YBX1 is dependent on AKT for nuclear translocation after phosphorylation at Ser102, including ovarian cancer cells and breast cancer cells." (PMID 38849679, 2024). "The AURKA-YBX1/hnRNPK complex correlates with poor breast cancer prognosis, and blocking nuclear AURKA shows promise in reversing oncogenic splicing events, highlighting YBX1’s significant role in this process." (PMID 38255791, 2024). "In conclusion, our findings discovered that the piR-YBX1/YBX1/MAPK axis suppresses the proliferation and metastasis of TNBC and therefore piR-YBX1 has the potential to be an effective therapeutic agent for breast cancer." (PMID 38182573, 2024). "As a potential RNA binding protein, YBX1 enhances the angiogenic ability of HUVECs by binding and promoting AC073352.1, a lncRNA significantly upregulated in breast cancer, sorting it into exosomes and mediating angiogenesis." (PMID 38255791, 2024). "YBX1 overexpression also induces constitutive activation of the epidermal growth factor receptor (EGFR), which contributes to the proliferation of breast cancer cells." (PMID 38255791, 2024). "The adriamycin (ADM)-selected breast cancer MCF-7/ADM cell line exhibited higher levels of ABCB1 and Y-box binding protein-1 (YB-1), and transfection of miR-137 reduced both YB-1 and ABCB1 levels." (PMID 39114355, 2024). "The targeted inhibitory effect of SU056 on YBX-1 has been confirmed in acute myeloid leukemia (AML), lung cancer, and breast cancer." (PMID 39062595, 2024). "YBX1 collaborates with oncogenic lncRNA SBF2-AS1, driving breast cancer cell proliferation via PI3K/AKT/mTOR." (PMID 38255791, 2024). "In another study on HER2-positive breast cancer, aloe-emodin (AE) extracted from rhubarb roots showed the ability to suppress the ILK/AKT/mTOR axis and thus reduce YBX1 expression and elicit positive anticancer activity." (PMID 38255791, 2024). "It spurs tumor growth by involving YBX1, activating GLO1, spotlighting YBX1’s critical role in breast cancer advancement." (PMID 38255791, 2024). "It interacts with YBX1, stabilizing its expression and influencing metastasis, suggesting AC073352.1 as a potential prognostic biomarker and therapeutic target in breast cancer." (PMID 38255791, 2024). "Although certain studies have indicated that elevated levels of YBX1 can enhance cancer cell growth in GBM and breast cancer cell lines, contrasting evidence suggests that enforced YBX1 expression actually suppresses cell proliferation." (PMID 38255791, 2024). "RT-PCR was conducted to examine YBX1 and hnRNPK implicated in RNA splicing regulation by virtue of AURKA mediation, which showed that YBX1 knockdown promoted GOLGA4 exon skipping, whereas hnRNPK knockdown promoted RBM4 exon inclusion in breast cancer cells." (PMID 37415951, 2023). "Research on bladder cancer, breast cancer, HCC, and oral squamous cell carcinoma revealed that ALYREF and YBX1 were upregulated as well." (PMID 36389669, 2022). "YBX1, as previously discussed, may also play a role in the drug resistance of breast cancer cells through promoting antiestrogen resistance, and decreasing the effectiveness of endocrine therapeutic drugs for estrogen receptor positive (ER-positive) breast cancer patients." (PMID 35721477, 2022). "Considering the YBX1 can stabilize mRNA, the impaired recognition by YBX1 will lead to the decay of PTPN2 and contribute to the development of breast cancer." (PMID 35456483, 2022).
breast carcinoma (continued). "Among these results, cytosine located in gene PTPN2 (chromosome 18: 12789928), which is a tumor suppressor gene with a low expression ratio in breast cancer, was a putative site regulated by NSUN2 and YBX1." (PMID 35456483, 2022). "In contrast to our findings the authors assume that regulation of RNA stability represents a major mechanism of YBX1-action in AML, similar to findings described in breast cancer." (PMID 34465866, 2022). "The tRF-2s derived from tRNA-Glu in breast cancer cells were shown to harbor YBX1 binding motifs and able to bind YBX1 protein, thus displacing the 3’UTR of oncogenic transcripts from YBX1 and suppressing the stability of oncogenic transcripts." (PMID 33041815, 2020). "Specifically, it has been observed that genes within the YBX1 and ENO1 regulons are strongly enriched for GWAS breast cancer eQTLs46." (PMID 31428694, 2019). "Western blotting showed that EYA2 overexpression induced the up-regulation of YBX1, EGFR, cyclin E, and PCNA in both these two breast cancer cell lines." (PMID 30761270, 2019). "Cellular IF assay also showed that EYA2 overexpression enhanced the protein abundance of YBX1, EGFR, and PCNA in both breast cancer cell lines." (PMID 30761270, 2019). "We searched a database for the top 500 genes that are positively or negatively correlated with YBX1 and with ESR1 in breast cancer patients." (PMID 30647855, 2018). "In addition, 2-tRFs (mainly from tRNAGlu, tRNAAsp, tRNAGly, and tRNATyr) can competitively bind to YBX-1 (also referred as YB-1) and block its interaction with oncogenic mRNAs, thereby reducing the stability of these mRNAs and eventually inhibiting metastasis of human breast cancer cells." (PMID 29748504, 2018). "Because YBX1 was identified as an oncoprotein in breast cancer via transgenic knock-in animal models of various types of breast cancer, it is therefore expected that YBX1 may play a specific and essential role in the tumorigenesis and malignant progression of breast cancer." (PMID 30647855, 2018). "Furthermore, YBX1 interacts with lncRNA SBF2-AS1 to modulate cell proliferation via the PI3K/AKT/mTOR signaling pathway, thus influencing the proliferation of breast cancer cells." (PMID 40799245, 2025). "RP11-162G10.5 recruits YBX1 to activate GLO1 transcription, regulating breast cancer progression." (PMID 40799245, 2025). "Similarly, a protein-dependent replacement mechanism was also confirmed in a previous study after induction by replacing 3'UTRs from the Y-box-binding protein 1 (YBX1), which inhibited the stability of multiple oncogenic transcripts in breast cancer cells." (PMID 38370372, 2024). "Additionally, Quercetin has been shown to reverse multidrug resistance (MDR) in breast cancer cells (MCF-7 and MCF-7/Dox) by nuclear translocation of Y-box binding protein 1 (YB-1), upregulating P-gp expression and killing cancer stem cells (CSCs)." (PMID 39287822, 2024). "Additionally, inhibiting YBX1 results in a significant reduction in the S phase content, along with a notable decrease in CDC6 (Cell Division Cycle 6) expression in breast cancer cells and chordoma cells." (PMID 38255791, 2024). "Notably, it has been observed that IL-6 stimulation can induce YBX1 expression, suggesting the existence of a positive feed-forward loop that contributes to the process of EMT in breast cancer cell lines." (PMID 38255791, 2024). "Such conditions may allow tRFs in breast cancer cells to bind to the oncogenic RBP, YBX1, and inhibit cancer metastasis." (PMID 36964534, 2023). "Finally, analysis of TCGA database revealed that the combined high expression of NSUN2, YBX1 and QSOX1 predicted the poorest overall survival in lung adenocarcinoma (LUAD), breast cancer (BRCA) and hepatocellular carcinoma (HCC)." (PMID 37161388, 2023).
breast carcinoma (continued). "A study showed that the YBX1 phosphorylation inhibitors including TAS0612 (multikinase inhibitor) and everolimus (rapamycin complex 1 inhibitor) mitigated antiestrogen resistance in breast cancer." (PMID 35721510, 2022). "Similar results were observed in other breast cancer cohorts in which YBX1 was elevated in TNBC compared to non-TNBC patients." (PMID 34440660, 2021). "In breast cancer MDA-MB-231 cells, YBX1 could regulate invasion and migration by regulating its downstream target CORO1C." (PMID 32695668, 2020). "Furthermore, the enhanced expression levels of YBX1 and its correlated gene CTPS1 were able to predict poor outcomes of breast cancer." (PMID 30647855, 2018). "With the exception of UQCRH and LRP8, the expression levels of genes positively correlated with YBX1, such as CTPS1, FMNL2, CDC20, B3GNT5, MTHFD1L, and CDCA8, were significantly and positively correlated with the expression level of YBX1 in 13 breast cancer cell lines." (PMID 30647855, 2018). "Interestingly, a majority of YBX1 and HIF1A positive populations in ER−/low breast cancers are also ST14/Prss14 high expressors." (PMID 27167193, 2016). "We previously reported that Y-box binding protein-1 (YB-1), a transcription/translation factor, was a marker of poor prognosis in a cohort of 490 patients with breast cancer, but the study was not large enough to subtype the cancers." (PMID 18925950, 2008). "Furthermore, YBX1 and ESR1 serve as biomarkers for adverse outcomes in breast cancer patients." (PMID 40799245, 2025). "In our previous study, Y-box binding protein-1 (YB1), a transcriptional activator, was identified as a novel interacting protein of BRD7 in breast cancer, and BRD7 suppressed cell proliferation and EMT-mediated invasion and metastasis in breast cancer by negatively regulating YB1." (PMID 41315221, 2025). "Additionally, the glycolysis signature showed positive correlations with mesenchymal-related genes in breast cancer patients, suggesting that crosstalk between glycolysis and the EMT may be regulated by YBX1." (PMID 34440660, 2021). "Moreover, through its N-terminus, BRD7 binds to Y box binding protein-1 (YB1), an oncogene that is upregulated in certain cancers; this in turn leads to ubiquitin-mediated degradation of YB1 in the MDA231 and MCF7 breast cancer cell lines." (PMID 32992509, 2020). "In the present study, enhanced YBX1 expression was mostly correlated with enhanced expression of genes involved in cell growth, cell cycle, survival and DNA synthesis, as well as decreased expression of ESR1 and various ESR1 effector genes in breast cancer patients and breast cancer cell lines." (PMID 30647855, 2018). "Similarly, in colorectal cancer, YBX1 binds to the promoter and acts as a transcriptional activator of the EGFR gene, mediating resistance to anti-ERBB2 therapy and preventing apoptosis in ERBB2-overexpressing breast cancer cells through a complex RSK-dependent mechanism." (PMID 40799245, 2025). "In addition, phosphorylation of YBX-1 Ser102 promotes the formation of the YBX-1/KLF5 transcriptional complex, which jointly regulates the expression of keratin 16 and lymphocyte antigen 6 family member D and promotes the proliferation of basal-like breast cancer cells." (PMID 39062595, 2024). "Furthermore, in breast cancer cells, transcription of DSCAM-AS1 was shown to be mainly activated by FOXA1 and was in turn able to affect expression of its regulators ERα and FOXA1 via interaction with YBX1, forming a positive feedback loop leading to breast cancer progression." (PMID 35885035, 2022). "It should be noted that the glycolysis signature was associated with poor prognoses in luminal and basal-like breast cancer patients, but not in the HER2 subtype, indicating that HER2-enriched breast cancer may have distinct molecular characteristics which are independent of YBX1 or glycolysis." (PMID 34440660, 2021).